RAC1 (Rac family small GTPase 1)
Diseases named in the same sentence as RAC1 in open-access papers (continued):
Sharing a sentence is not in itself a finding about the gene and the disease.
tumor (continued). "In the case of the GTPase Rac1 (Ras-related C3 botulinum toxin substrate 1), it resulted in the expression of the isoform Rac1b which sustains tumor survival; SRPK1 downregulation was tumor suppressive through downregulating the expression of Rac1b." (PMID 31861708, 2019). "Starting from this observation, through bioinformatic analysis we focused our attention on miR-31-5p, which is reported to regulate the expression of HIF1AN, RhoA and RAC1 in different tumor cell lines and hMSCs." (PMID 30925808, 2019). "Once activated, Rab5 recruits a number of interacting proteins, including Rac1 and Tiam1, which play an important role in vesicle transport, cytoskeletal remodeling, and tumor metastasis." (PMID 31572059, 2019). "The tumor-promoting effect of RAC1 is based primarily on its pro-EMT, proinvasive and prometastatic function in several tissues." (PMID 31817229, 2019). "These factors have been showed to be involved in chemotaxis (CXCR485) and locomotion (ROCK1/2, Acta2, Pak-1, Rac1, and RhoA28) of stromal cells to help migration of these cells to tumor niches." (PMID 31391540, 2019). "Mechanism studies showed that TUFT1 promoted tumor cell metastasis and stemness by up-regulating the Rac1/β-catenin pathway." (PMID 31338333, 2019). "The broad impact of Rac1 on tumor cell behavior has led to consideration of Rac1 as a potential therapeutic target." (PMID 30261690, 2018). "The overexpression of CRKI/II and RAC1 commonly lead to relative higher tumor cell migration and invasions." (PMID 29802377, 2018). "Xenograft studies of BL-41 cells in immunodeficient NOG mice revealed that silencing of Rac1 markedly suppressed tumor growth compared to Rac1-proficient BL-41 cells." (PMID 30558116, 2018). "The elevation of PTEN inhibits PIP3/PIP2 ratios and then interferes with the activation of RAC1, which enhances cell polarization, and thus, this contributes to directed tumor cell migration as well as tumor invasion." (PMID 29954406, 2018). "The contact with CM derived from tumour‐activated BM‐MSCs induces a significant decrease of bound Rac1‐GTP with a parallel increase of bound RhoA‐GTP in OS cells." (PMID 29517849, 2018). "Because chemotherapeutic drugs can kill tumor cells by activating Rac1/JNK pathway, we suspect that tumors with RCC2 overexpression would be more resistant to these drugs." (PMID 29321004, 2018). "Based on the known activities of Rac1, this protein can play important roles in multiple steps of tumor development, dissemination and disease recurrence." (PMID 30261690, 2018). "The tumor suppressor APC is mutated in sporadic and familial colorectal tumors, and wild-type APC interacts with the Rac1-specific guanine–nucleotide exchange factor (GEF) Asef and Asef2." (PMID 30514346, 2018). "Tumor migration and invasion are strictly regulated by actin cytoskeleton modulated by Rho family of small GTPases, including RAC1, Cdc42, and RhoA in space timely." (PMID 29802377, 2018). "For this analysis we included Decorin that shows increased expression in the tumor capsule, Hepar 1 antigen that is evenly expressed across the specimen and RAC1 that shows the gradient of expression from the tumor center to the periphery of the specimen." (PMID 29363612, 2018). "There is strong emerging evidence that Rac1 also contributes to the tumor stem cell phenotype, epithelial to mesenchymal transition (EMT), angiogenesis, and chemoresistance." (PMID 30261690, 2018). "FilGAP and ArhGAP22 activation by RhoA/ROCK have been suggested to play a role in the RhoA/Rac1 antagonism of tumor cells, but inactivation of specific GEFs (p115RhoGEF, LARG, PDZ-RhoGEF) can also contribute to reduced Rac1 activation." (PMID 30048510, 2018). "Rac1 plays a pivotal role in tumor development, especially in the invasiveness and metastasis of tumors." (PMID 30534358, 2018). "Rac1 is highly expressed in a number of cancer cell lines and plays an important role in regulating tumor progression." (PMID 30186591, 2018).
tumor (continued). "Univariate Cox regression analysis revealed that increased tumor size, presence of LNM, overexpression of β1 integrin and/or Rac1, and polarity reversal are associated with worse DFS in patients with IMPC (P < 0.05)." (PMID 29435106, 2018). "Because Rac1 is responsive to an array of signals, Rac1 is capable of driving multiple steps of tumor development, dissemination and recurrence." (PMID 30261690, 2018). "In contrast, BCAR3 and cas interact to activate Rac1, rapidly breaking down adhesion and resulting tumor invasion." (PMID 30563570, 2018). "Partial responses are seen in patients with pre-treatment PTEN tumour loss, with pre-treatment AKT phosphorylation, and with pre-treatment AKT3 and RAC1 activating mutations." (PMID 30237495, 2018). "Further studies showed that RCC2 over-expression in tumor cells led to attenuation of spontaneous- or STS-induced apoptosis and the apoptosis resistance was associated with decreased Rac1 activation." (PMID 29321004, 2018). "In this study, we found that RCC2 plays a role in tumor cell death by blocking the Rac1- initiated apoptosis." (PMID 29321004, 2018). "Mechanically, TIPE2 suppressed tumor invasiveness by inhibiting Rac1, which subsequently decreased the expression of uPA and MMP9." (PMID 30186591, 2018). "It is known that the uPA and MMP9 are important Rac1 downstream effectors that are responsible for degrading the extracellular matrix components, which is essential for the invasiveness of tumor cells." (PMID 30186591, 2018). "It is evident that Rac1 plays a pivotal role in regulating tumor invasiveness, and uPA and MMPs have been demonstrated to be the downstream effectors of Rac1 signaling." (PMID 30534358, 2018). "The significance of Rac1 ubiquitylation was revealed by the discovery of HACE1 ubiquitin ligase as a tumor suppressor." (PMID 30544910, 2018). "Our work showed the positive correlations of ANXA5 level with CRKI/II and RAC1, critical molecules in integrin pathway, in tumorous tissues from HCC patients." (PMID 29802377, 2018). "The levels of CRKI/II and RAC1 were reduced in tumor tissues from mice transplanted with Hca-P cells with stable ANXA5 knockdown." (PMID 29802377, 2018). "There is increasing evidence suggesting that mouse double minute 2 homolog (MDM2), insulin-like growth factor 1 (IGF1), signal transducer and activator of transcription 1 (STAT1), and Rac family small GTPase 1 (RAC1) are involved in tumor progression." (PMID 29651441, 2018). "It has been demonstrated that Rac1 regulates various downstream effector molecules related to tumor aggressiveness, such as MMP9 and uPA." (PMID 30186591, 2018). "All these results indicate that TIPE2 is a potential biomarker for predicting tumor aggressiveness and suppresses tumor invasiveness in a Rac1-dependent manner in PTC." (PMID 30186591, 2018). "Mutual inter-positive correlations were apparently established for the levels of ANXA5, CRKI/II and RAC1 in tumorous tissues from patients." (PMID 29802377, 2018). "Here we demonstrated that TIPE2 suppressed tumor aggressiveness via inhibiting Rac1, which subsequently decreased the expression of uPA and MMP9 in PTC cells." (PMID 30186591, 2018). "Tumor cell-cell adhesions are mediated by E-cadherin maintenance of cell-cell junctions that depend on a Rac1-Tiam1 GEF-IQGAP1 effector complex and promote an anti-migratory phenotype." (PMID 30261690, 2018). "Of 48 paraneoplastic benign breast tissue samples, 30 (62.5%) demonstrated high β1 integrin levels and 29 (60.4%) demonstrated high Rac1 levels." (PMID 29435106, 2018). "Taken together, it is evident that deregulation of Rac1 signaling can drive tumor initiation, progression and metastasis, making it an attractive therapeutic target." (PMID 27442895, 2017). "The signalling pathways coordinated with RhoA and Rac1 activities play pivotal roles in tumor metastasis." (PMID 28841878, 2017).
tumor (continued). "To investigate the function of the WxxxE motif in the interaction with Rac1 and host tumor progression, we synthesized a 35-amino acid WVLGE-containing polypeptide derived from a cell-penetrating peptide derived from the azurin protein." (PMID 28549350, 2017). "It has long been established that Rac1 drives tumor initiation, via serving as a Ras downstream effector, with in vitro data demonstrating the requirement of Rac1 for full oncogenic Ras transformation of NIH3T3 cells." (PMID 27442895, 2017). "Migration, in part regulated by RhoA, Rac1 and cdc42 small G-proteins, has a pivotal role in tumor progression and metastasis formation." (PMID 28562340, 2017). "It was also shown that Rac1 nuclear accumulation mediates tumor cell invasion due to increased RhoA signaling in the cytoplasm." (PMID 27442895, 2017). "In conclusion, our studies revealed the other side of XIAP in the control of Rho GTPases (especially Rac1 and Cdc42), the prime drivers of tumor cell migration and invasion." (PMID 28661476, 2017). "The E3 ubiquitin ligase HACE1 is a potent tumor suppressor that controls cell proliferation and ubiquitylates the small GTPase Rac1 to target it to proteasomal degradation." (PMID 28317937, 2017). "Our results provide, for the first time, evidence for a tumor suppressing function of Rac1 in the epidermis." (PMID 28277539, 2017). "Although no RIT1, RRAS2, or MRAS mutations were found in the TCGA BC dataset, one tumor with undetermined ER and HER2 statuses harbored a RAC1 (P69S) mutation, and one TNBC tumor harbored a RHOB (D13Y) mutation." (PMID 28636652, 2017). "The motility and metastasis of tumor cells are controlled by RhoA and Rac1, and activation of ERK participates in stress fiber formation through inhibition of RhoA." (PMID 28841878, 2017). "The functional antagonism of RAC1b and RAC1 in controlling TGF-β signaling in conjunction with appropriate changes in their relative activities during tumor progression also represents a potential mechanism to explain the TGF-β paradox." (PMID 28499439, 2017). "The attenuated invasive capacity of GBM tumors following treatment with CLOVA cocktail was associated with decrease in activating phosphorylation of (pFAKY397 and pFAKY861) and with alteration in subcellular localization of active Rac1 in tumor cells." (PMID 28423558, 2017). "The members of the Ras superfamily of small GTPases, such as Rac1, Cdc42, and RhoA, are adhesion and growth factor-activated molecular switches that play important roles in tumor development and progression." (PMID 28811522, 2017). "The observation that ALK5 protein was more abundant in Rac1-depleted cells is particularly interesting since altering receptor expression is a prominent mechanism through which tumour cells can modulate their sensitivity to TGF-β44." (PMID 29229918, 2017). "We also confirmed that RAC2 is co-expressed with CD34-positive cells and that RAC1 is strongly expressed at the tumor-stroma border of Tgfbr2 cKO SCC." (PMID 28219480, 2017). "In this study, we show that PAD2 depletion or inhibition suppresses tumor cell migration, alters tumor cell morphology, and suppresses the expression of the cytoskeletal regulatory proteins: RhoA, Rac1, and Cdc42." (PMID 28549415, 2017). "Since p62 has been described to induce a more advanced tumor phenotype by promoting RAC1-induced ROS generation, RAC1 mRNA expression was measured in the eight BTC cell lines." (PMID 29163784, 2017). "SIRT1 has been shown to interact with and activate TIAM1 (T-cell lymphoma invasion and metastasis 1) and Rac1 in tumor cells, in parallel with TIAM1 acetylation." (PMID 29074993, 2017). "The mechanism of the effects of BGN on tumor cell migration is likely to be mediated by the Rac1-mediated TGF-β signaling pathway, thus suggesting a role of BGN in the development of EMT29." (PMID 28687755, 2017).
tumor (continued). "It has been proposed that ANGPTL2 secreted from cancer cells activates the integrin α5β1/Rac1 pathway, promoting both autocrine and paracrine effects, increasing tumour cell invasion, motility, tumour angiogenesis, and thus tumour metastasis." (PMID 29138671, 2017). "Cytoskeleton-regulating proteins, including rhodopsin (RHO), CDC42 and ras-related C3 botulinum toxin substrate 1 RAC1 (RAC1), which are members of the RAS family due to high similarity, are implicated in tumor metastasis." (PMID 28179017, 2017). "When activated by sCPE, phosphorylated RPS6 contributed to decrease-, and when pharmacologically inhibited, dephosphorylated RPS6 resulted in an increase of GTP-bound Rac1, therefore affecting tumor cell motility." (PMID 28978054, 2017). "have shown that impeded Rac1 nuclear export—which drives nuclear actin polymerisation controlling nuclear shape and organization—alters the cytoplasmic ratio of Rac1 and Rho, increasing cytoplasmic RhoA signaling and driving tumor invasion." (PMID 28152338, 2017). "Fibronectin stimulation has been shown to activate RAC1 which also signals the cytoskeleton-dependent processes taking place during the cell migration in tumor cells." (PMID 27902969, 2017). "We present evidence for the first time to prove that RAC1 GTP-ase signals WP-stimulated ID-MA tumor cell phenotypes, migration, and invasion in TNBC." (PMID 27902969, 2017). "The molecular basis for radiosensitization of tumor cells and concomitant radioprotection of normal cells by statins and/or Rac1 inhibition remains obscure." (PMID 28796249, 2017). "Animal experiments support a requirement for Rac1 in tumor formation and growth in many different tumor models." (PMID 27104658, 2016). "Taken together, our results indicate that integrin β6 promotes tumor invasiveness in a Rac1-dependent manner and is a potential biomarker for tumor metastasis." (PMID 27440504, 2016). "Another recent study showed that Rac1 affects stem cell behavior to drive oncogenic progression, by reducing the differentiation of tumor cells." (PMID 27104658, 2016). "The early endosome protein Rab5 is a small GTPase that promotes integrin trafficking, focal adhesion turnover, Rac1 activation, tumor cell migration and invasion." (PMID 27121131, 2016). "The inhibition of either the expression or the activity of Rac1, Pak1 or Rock1 leads to the suppression of tumor cell growth, invasion and metastasis." (PMID 26871290, 2016). "In tumor cells invading a rigid extracellular matrix environment, an upregulation of Rac1 activity and a concomitant downregulation of RhoA has been noted, similar to the signaling which has been observed during neural crest migration." (PMID 27589803, 2016). "Western blot analysis showed that Rac1 was down-regulated in tumors treated with dtACPPD/shRac1 (76.4% down-regulation, p < 0.01), suggesting the ideal tumor-targeting ability of the dtACPPD/shRac1nanoparticles." (PMID 27791203, 2016). "Consistently, ectopic expression of NKD1 significant decreased Rac1 protein level in transplanted tumor tissue." (PMID 27231134, 2016). "Successful inhibition of Rac1 expression using RNAi leads to decrease of blood vessel density and slower of tumor growth." (PMID 27791203, 2016). "PREX2, a GEF for RAC1, has been shown to be associated with PTEN pathway, where the suppression of this GEF is necessary for PTEN tumor suppressor activity." (PMID 27597870, 2016). "The in vivo biodistribution, tumor-targeting characteristics and Rac1 silencing efficacy of dtACPPD/shRac1 were investigated in an HCT-116 cell tumor model in BALB/c nude mice." (PMID 27791203, 2016). "Tumor cells produced VEGF activates endothelial Rac1, resulting the increases in endothelial permeability and transendothelial migration of themselves." (PMID 25991673, 2015).
tumor (continued). "Mechanistic dissection revealed that miR-203 mediated cell proliferation, adhesion and invasion in vitro, and tumor growth in vivo, as evidenced by reduced RAC1, p-PAK1, and p-MEK1 expression." (PMID 25636908, 2015). "Together, these data suggest that Rac1 inhibition alone is insufficient to control tumor metastasis." (PMID 25888632, 2015). "It is well established that Ras homologous (Rho) GTPases family proteins, like Rac1 and RhoA, play a key role in cell migration and tumor metastasis by regulating actin dynamics and cell-cell adhesion." (PMID 26156017, 2015). "To confirm the effect of Rac1 activity on tumor metastasis in vivo, we examined lung metastasis in mice injected with Rac1N17-transfected or NSC23766-treated B16F10 cells." (PMID 25888632, 2015). "Given that Rap1 activation is involved in tumor metastasis through the activation of Rac1, we next examined the effect of NSC23766 on Rap1 activation." (PMID 25888632, 2015). "Since our tumor model of HER2 overexpression and HACE1 loss is driven by Rac1 hyperactivation, we evaluated the antitumor activity of EHT1864 in orthotopic-implanted MCF12A-HER2 shHACE1 cells." (PMID 25659579, 2015). "Tang and colleagues reported that the over-expression of eukaryotic initiation factor 5A2 enhanced cell motility and promoted tumor metastasis by activating RhoA/Rac1 to stimulate the formation of stress fibers and lamellipodia in HCC." (PMID 26498692, 2015). "Collectively, the present study opens up the new therapeutic potential of targeting the Rac1 pathway to control metastasis of tumor." (PMID 25991673, 2015). "Rho GTPases, members of the Ras superfamily of small GTPases such as Rac1, Cdc42, and RhoA, are adhesion and growth factor–activated molecular switches that play important roles in tumor development and progression." (PMID 26371759, 2015). "HACE1 loss coupled with the overexpression of a Rac1 activator such as HER2 results in hyperactivation of Rac signaling and is sufficient to transform normal mammary epithelial cells allowing tumor formation in mice." (PMID 25659579, 2015). "This triggers non-canonical Wnt responses, that is, suppresses the β-catenin/TCF/LEF pathway and tumorigenesis, but enhances PI3K-Akt and Rac1 signals and tumor cell invasiveness." (PMID 26126266, 2015). "Fibronectin expression, activation of the FAK/Rac1/cdc42 axis downstream of fibronectin, and tumor migration were concomitantly induced by EGF." (PMID 25595899, 2015). "It is also shown that deregulation of the miRNAs that regulate the Rac1 signaling can facilitate tumor cells to acquire a metastatic feature." (PMID 25361001, 2014). "Rac1 GTPase participates in regulating the migration, invasion, transformation, growth, and survival of tumor cells." (PMID 25091805, 2014). "We found that when Rac1 activity was inhibited by NSC23766, fewer tumors were observed in the DMBA/TPA mouse model, suggesting involvement of Rac1 activity in tumor formation." (PMID 24962779, 2014). "DEPDC1B plays a regulatory role by functioning as a GEF that activates Rac1 proteins and triggers migration in normal cells and invasion in tumor cells." (PMID 25091805, 2014). "Hyperactivation of Rac1 in SCC tissues correlates with keratin 17 overexpression Treatment of DMBA/TPA results in tumor development and is accompanied by the induction of protumorigenic inflammation, which augments Wnt/β-catenin signaling." (PMID 24962779, 2014). "To evaluate ERBB4 downstream signalling in vivo, we compared Akt, FAK and Rac1 activity in implantation site tumours isolated from mice implanted with CHLA-10 control versus CHLA-10 ERBB4 kd cells." (PMID 23681745, 2013). "Specific GAPs can inhibit the activation of Cdc42, Rac1 and RhoA by increasing intrinsic GTPase activity, leading to suppression of tumor formation." (PMID 23538840, 2013). "Collectively, human TIPE2 is an endogenous inhibitor of Rac1 by which it functions as a tumor suppressor to control cell proliferation, migration and invasion." (PMID 24274578, 2013).